GCNT4 (glucosaminyl (N-acetyl) transferase 4)
Description:
Glycosyltransferase that mediates core 2 O-glycan branching, an important step in mucin-type biosynthesis. Does not have core 4 O-glycan or I-branching enzyme activity.
Synonyms: C2GnT3; LINC01336
Tractability: Antibody: UniProt predicts a signal peptide or a membrane-spanning region.
Gene: Protein-coding gene on chromosome 5 (75,025,346 to 75,054,224, reverse strand). Ensembl gene ENSG00000176928.
Subcellular location: Golgi apparatus membrane
Subcellular location (Human Protein Atlas): Golgi apparatus; Nucleoplasm
Pathways (Reactome):
Metabolism of proteins: O-linked glycosylation of mucins
Gene Ontology:
Molecular function: acetylglucosaminyltransferase activity; beta-1,3-galactosyl-O-glycosyl-glycoprotein beta-1,6-N-acetylglucosaminyltransferase activity; N-acetyllactosaminide beta-1,6-N-acetylglucosaminyltransferase activity; glycosyltransferase activity; UDP-glycosyltransferase activity
Biological process: carbohydrate metabolic process; protein O-linked glycosylation; protein O-linked glycosylation via N-acetyl-galactosamine
Cellular component: Golgi apparatus; Golgi membrane; membrane
Genetic constraint (gnomAD): Loss-of-function variants: 19 observed, 34.84 expected, observed/expected ratio (o/e) 0.55, 90% interval 0.38 to 0.8. The synonymous counts are far from expectation, so gnomAD's model fits this gene poorly and the ratio says little. Missense variants: 503 observed, 553.2 expected, observed/expected ratio (o/e) 0.91, 90% interval 0.84 to 0.98. Synonymous variants: 158 observed, 203.05 expected, observed/expected ratio (o/e) 0.78, 90% interval 0.68 to 0.89.
Homologues: Orthologues: chimpanzee GCNT4 (99% identical), macaque GCNT4 (97% identical), pig GCNT4 (89% identical), dog GCNT4 (87% identical), guinea pig GCNT4 (87% identical), rat Gcnt4 (83% identical), rabbit GCNT4 (82% identical), mouse Gcnt4 (82% identical), tropical clawed frog gcnt4 (58% identical), zebrafish gcnt4a (55% identical), zebrafish gcnt4b.2 (49% identical), zebrafish gcnt4b.1 (47% identical), and 19 more. Paralogues in human: GCNT1 (38% identical), GCNT3 (37% identical), GCNT2 (34% identical), GCNT7 (25% identical), XYLT1 (21% identical), XYLT2 (20% identical), WSCD2 (10% identical), WSCD1 (10% identical).
Diseases named in the same sentence as GCNT4 in open-access papers:
GCNT4 is named in the same sentence as 20 diseases in open-access papers, as found by Europe PMC text mining. Sharing a sentence is not in itself a finding about the gene and the disease. The quoted sentences say what the papers report.
gastric cancer (5 papers, 2021 to 2025). A primary or metastatic malignant neoplasm involving the stomach. "GCNT4 is markedly downregulated in gastric cancer, with low expression associating with poorer OS and DFS." (PMID 41562091, 2025). "One study suggested that GCNT4 was significantly downregulated in gastric cancer and was associated with a poor prognosis." (PMID 34696660, 2021). "But studies on gastric cancer have suggested that GCNT4 can act as a tumor suppressor and induce tumor growth arrest." (PMID 40352586, 2025). "Further studies have revealed that overexpression of GCNT4 can prevent the growth of gastric cancer cells by regulating the TGF-β1/SMAD3 pathway." (PMID 36158645, 2022). "Overall, this study revealed that miR-130a-3p aggravated gastric cancer cell proliferation, migration, and invasion by reducing GCNT4 expression and activating the TGF-β1/SMAD3 signaling pathway." (PMID 34696660, 2021). "Mechanistically, miR-130a-3p was found to facilitate the malignant behavior of gastric cancer by targeting GCNT4." (PMID 34696660, 2021). "Overall, results showed that targeting of GCNT4 by miR-130a-3p promoted the progression of gastric cancer." (PMID 34696660, 2021). "Accordingly, miR-130a-3p bound 3ʹ UTR of GCNT4 and suppressed the repressing role of GCNT4 on the malignant behavior of gastric cancer cells." (PMID 34696660, 2021). "Overexpression of GCNT4 abrogated the promoting effect of miR-130a-3p mimic on the proliferative, migratory, and invasive phenotypes of gastric cancer cells." (PMID 34696660, 2021). "This indicated that GCNT4 overexpression in gastric cancer cells inhibited the TGF-β1/SMAD3 signaling pathway activated by miR-130a-3p upregulation." (PMID 34696660, 2021). "The results showed that miR-130a-3p levels were increased, while GCNT4 levels were reduced in gastric cancer tissues and cell lines." (PMID 34696660, 2021). "The findings of this study have important implications for the selection of therapeutic targets for gastric cancer treatment involving miR-130a-3p/GCNT4 and TGF-β1/SMAD3 axes." (PMID 34696660, 2021). "Using bioinformatics analysis, miR-130a-3p and GCNT4 were identified as the genes of interest with respect to gastric cancer." (PMID 34696660, 2021). "This indicates that miR-130a-3p participates in the regulation of gastric cancer cell behavior by targeting GCNT4 and inducing activation of the TGF-β1/SMAD3 signaling pathway." (PMID 34696660, 2021). "This study provides important strategies for the selection of therapeutic targets for gastric cancer treatment involving miR-130a-3p/GCNT4/TGF-β1/SMAD3 axis." (PMID 34696660, 2021). "Among the five interacting genes, GCNT4 has been extensively studied in human cancer, including gastric cancer, and has been reported to suppress gastric cancer cell proliferation phenotype only once." (PMID 34696660, 2021). "To elucidate the function of the miR-130a-3p-GCNT4 axis in gastric cancer, we transfected GCNT4 overexpression (OE) and miR-130a-3p-mimic into MKN45 and AGS cells." (PMID 34696660, 2021). "Dysregulation of glucosaminyl (N-acetyl) transferase 4 (GCNT4) gene and miR-130a-3p gene has been reported in the development of gastric cancer." (PMID 34696660, 2021). "To identify a potential upstream miRNA regulator of GCNT4 in gastric cancer, we selected a list of TargetScan-predicted targets of GCNT4 from the GSE93415 data series, an miRNA microarray profile in gastric cancer." (PMID 34696660, 2021). "Biological roles of miR-130a-3p and GCNT4 were determined using cell proliferation, migration, and invasion assays in gastric cancer cells." (PMID 34696660, 2021). "Reverse transcription quantitative polymerase-chain reaction measured miR-130a-3p and GCNT4 levels in gastric cancer tissues and cells." (PMID 34696660, 2021). "Mechanistically, miR-130a-3p suppressed gastric cancer genesis by inhibiting GCNT4 expression and activating the TGF-β1/SMAD3 signaling pathway." (PMID 34696660, 2021).
gastric cancer (continued). "In line with previous investigations, we found a low level of GCNT4 in gastric cancer tissues and cells." (PMID 34696660, 2021). "GCNT4 overexpression suppresses cell proliferation by arresting the cell cycle in gastric cancer." (PMID 41562091, 2025). "Previous studies have reported decreased expression of GCNT4 in gastric cancer tissues." (PMID 36158645, 2022). "Our RT-qPCR results demonstrated the low expression of GCNT4 in gastric cancer tissues." (PMID 34696660, 2021). "We elucidated the function of the miR-130a-3p-GCNT4 axis in gastric cancer." (PMID 34696660, 2021). "Therefore, we investigated the expression of miR-130a-3p and GCNT4 in gastric cancer tissues and their effects on the proliferation, migration, and invasion of the cancer cells." (PMID 34696660, 2021). "However, the mechanism of the interaction between miR-130a-3p and GCNT4 in gastric cancer requires further evaluation." (PMID 34696660, 2021). "We hypothesized that miR-130a-3p facilitates gastric cancer progression by downregulating GCNT4, which blocks the activation of the TGF-β1/SMAD3 signaling pathway." (PMID 34696660, 2021). "Thus, in this study, we investigated the effects of miR-130a-3p and GCNT4 in human gastric cancer cell lines and normal gastric epithelial GES-1 cells." (PMID 34696660, 2021). "We hypothesized that miR-130a-3p promotes the progression of gastric cancer by downregulating GCNT4, which blocks the activation of the TGF-β1/SMAD3 signaling pathway." (PMID 34696660, 2021). "Therefore, we elucidated the role of the miR-130a-3p/GCNT4/TGF-β1/SMAD3 axis in gastric cancer genesis, which could provide potential therapeutic targets for gastric cancer involving both miR-130a-3p and GCNT4." (PMID 34696660, 2021). "However, functions of both miR-130a-3p and GCNT4 in the development of gastric cancer remain unknown." (PMID 34696660, 2021). "Altogether, we proposed that targeting of GCNT4 and activation of the TGF-β1/SMAD3 signaling pathway by miR-130a-3p enhanced the growth of gastric cancer cells." (PMID 34696660, 2021). "The targeting relationship was supported by the downregulation of GCNT4 expression in gastric cancer tissues and its negative correlation with the miR-130a-3p expression levels." (PMID 34696660, 2021). "Upregulation of GCNT4 effectively reduced cell growth in MKN45 and AGS gastric cancer cells." (PMID 34696660, 2021).
breast carcinoma (4 papers, 2017 to 2025). "High expression of GCNT4 has been associated with associated with poor prognosis in colorectal and breast cancer." (PMID 40352586, 2025). "Conversely, underexpression of PLAGL1 and GCNT4 were found in all three types of breast cancer." (PMID 36788602, 2023). "With respect to the O-GalNAc pathway, we observed alterations in several related glycogenes including the downregulation of GCNT4, GALNT13, GALNT16 and C1GALT1, and upregulation of ST3GAL1, ST6GALNAC4 and GAL3ST2 in Her2+ breast cancer tissue." (PMID 36282863, 2022).
pancreatic cancer (3 papers, 2020 to 2025). "To select suitable pancreatic cancer cells for the assay, we analyzed the expression of genes B3GNT6 (encoding β3Gn-T6) and MUC5AC, together with genes encoding core 2 synthases (GCNT1, GCNT3, and GCNT4) by qRT-PCR." (PMID 33253272, 2020). "GCNT4 is a member of the GCNT family that participates in cancer pathologies, such as colon cancer and pancreatic cancer." (PMID 34696660, 2021).
COVID-19 (2 papers, 2022 to 2023). A disease caused by infection with severe acute respiratory syndrome coronavirus 2. "High levels of circulating GCNT4, RAB14, C1GALT1C1, CD207 and ABO have also been previously suggested to be causally associated with an increased risk of suffering from critical COVID-19, with comparable odds ratios varying from 1.12 to 1.35." (PMID 37958866, 2023).
cervical cancer (1 paper, 2025). A primary or metastatic malignant neoplasm involving the cervix. "GALNT12 and GCNT3 had HRs greater than 1, indicating that they were risk factors for cervical cancer, whereas GCNT4 and NPL had the reverse effect." (PMID 40352586, 2025). "This study utilized bioinformatics analysis based on public databases to identify key prognostic genes associated with cervical cancer, including GALNT12, GCNT4, and NPL." (PMID 40352586, 2025). "The findings from qRT-PCR demonstrated that GCNT4 and NPL were considerably overexpressed in the cervical cancer group." (PMID 40352586, 2025). "The outcomes of qRT-PCR revealed that GCNT4 and NPL were substantially increased in cervical cancer group, which corresponded to the expression trend in GSE63514 dataset." (PMID 40352586, 2025). "This study identified three key prognostic sialylation-related genes, GALNT12, GCNT4 and NPL, which showed significant differences in expression between cervical cancer samples and normal samples." (PMID 40352586, 2025). "In this research, GALNT12, GCNT4 and NPL were discovered as sialylation-related prognostic genes in cervical cancer, providing novel pathways for detection and treatment." (PMID 40352586, 2025).
clear cell renal cell carcinoma (1 paper, 2025). "GCNT4 has a significant impact on the prognosis of patients with clear cell renal cell carcinoma, and patients with high expression of GCNT4 have significantly increased survival time." (PMID 41155476, 2025). "We found that the expression of GCNT4 was significantly downregulated in clear cell renal cell carcinoma." (PMID 41155476, 2025).
gastric tumor (1 paper, 2021). "GCNT4 mRNA and protein expression in gastric tumor tissues were downregulated compared to that in normal tissues." (PMID 34696660, 2021).
hepatic cancers (1 paper, 2020). "For instances, MGAT1, MGAT4A, and GXYLT2 are unfavorable prognostic markers, while MAN1C1, GCNT4, and STT3B are favorable markers in non-hepatic cancers." (PMID 32850363, 2020).
renal carcinoma (1 paper, 2025). A carcinoma arising from the epithelium of the renal parenchyma or the renal pelvis. "High expression of GCNT4 is associated with better survival prognosis and affects acetylation by regulating O-GlcNAc modification levels, inhibiting the proliferation and migration of renal cancer cells, providing a new potential target for the treatment of ccRCC." (PMID 40563096, 2025). "After that, we explored the role of GCNT4 gene in renal carcinogenesis by overexpressing GCNT4 in three renal cancer cell lines (OSRC2, 786-O and A498 cell lines)." (PMID 40563096, 2025). "This study demonstrated that after overexpression of GCNT4, the proliferation, invasion, and migration of three renal cancer cell lines (OSRC2, 786-O, and A498) were significantly inhibited." (PMID 40563096, 2025). "Therefore, we explored the molecular mechanism of GCNT4 in the development of renal cancer by detecting the level of intracellular O-GlcNAc modification." (PMID 40563096, 2025). "Overexpression of GCNT4 significantly inhibited the proliferation, invasion, and migration of renal cancer cells and may affect acetylation by regulating the levels of O-GlcNAc modification in cells." (PMID 40563096, 2025).
tumor (5 papers, 2021 to 2025). "High expression of GCNT4 was associated with better survival prognosis and was expressed at higher levels in normal tissues than tumor tissues." (PMID 40563096, 2025). "Analytical results revealed TYMP and HS3ST2 in tumor samples were significantly upregulated and GCNT4 and FUT3 were significantly downregulated." (PMID 41155476, 2025). "The Box plot and scatter plot of GCNT4 expression levels showed that GCNT4 expression levels were generally higher in normal tissues than in tumor tissues." (PMID 40563096, 2025). "The results of transwell assay showed that the GCNT4 overexpression groups all had significant inhibition of tumor cell migration and invasion." (PMID 40563096, 2025). "As shown in the IHC images, the expression of GCNT4 was significantly lower in tumor tissues compared to normal tissues." (PMID 40563096, 2025). "TYMP and GCNT4 were experimentally validated as key genes, functioning as oncogenic and tumor-suppressive factors." (PMID 41155476, 2025). "We then examined the differences in GCNT4 expression in normal and tumor tissues." (PMID 40563096, 2025). "The results of CCK8 proliferation assay showed that the absorbance of all overexpression groups was significantly reduced and the cell viability was significantly reduced compared with the control group, revealing that GCNT4 could inhibit the proliferation of tumor cells." (PMID 40563096, 2025). "Abnormal expression of the GCNT4 gene may affect the function of NOD-like receptors by influencing glycosylation in the tumor microenvironment, thereby affecting tumor immune escape." (PMID 40352586, 2025). "Notably, GCNT4 and GCNT3 may cooperatively regulate the structure and function of glycans through synergistic effects in the O-glycosylation process, thereby influencing tumor cell adhesion, migration, and immune evasion." (PMID 40352586, 2025). "Finally, we found a negative correlation between miR-130a-3p and GCNT4 expression in tumor tissues." (PMID 34696660, 2021).
infection (3 papers, 2009 to 2018). The state of being infected such as from the introduction of a foreign agent such as serum, vaccine, antigenic substance or organism. "Soon after infection of the bovine GI tract, both C. oncophora and O. ostertagi induced expression of the mucin glycan biosynthesis enzyme gene Gcnt3, in addition to Gcnt4 and A4gnt induced by O. ostertagi, further supporting that changes in the mucus niche occur during infection." (PMID 29912166, 2018). "For the glycosyltransferases involved in mucin biosynthesis, GCNT3 and GCNT4, both involved in the synthesis of core structures, were found to be up-regulated during infection, while C1GALT1 a key enzyme for the core 1 formation was not affected by the infection." (PMID 21569362, 2011).
neurodegenerative disease (1 paper, 2025). A disorder of the central nervous system characterized by gradual and progressive loss of neural tissue and neurologic function. "Based on the evidence from the Open Target Platform, GCNT4 and MAST2 are related to neurodegenerative disease and measurements of erythrocyte count, BMI, LDL and TC; whereas CRTAC1 is related to body fat percentage and measurements of HDL and TG." (PMID 40830362, 2025).
GCNT4 also shares sentences with these, for which no sentence is quoted: cancer (2 papers); colon cancer (2); Alzheimer disease (1); esophageal cancer (1); hepatocellular carcinoma (1); melanoma (1); prostate carcinoma (1); Stroke (1).